IL1A (interleukin 1 alpha)
Diseases named in the same sentence as IL1A in open-access papers (continued):
Sharing a sentence is not in itself a finding about the gene and the disease.
infection (continued). "Cultured epithelial cell lines (HeLa, SiHa, HT-29, SW620, and primary endocervical) infected with Ct secrete proinflammatory cytokines (IL-8, IL-6, GM-CSF, and GROα/CXCL1), but cytokine secretion is delayed until 20–24 h post-infection, after lysing cells release IL-1α." (PMID 30524442, 2018). "As HIV is known to show enhanced infection in presence of genital inflammation and epithelial breach increased inflammation (higher IL-1α and IP-10), coupled with impaired wound healing could be detrimental for these women in terms of HIV acquisition." (PMID 29894487, 2018). "However, the concentrations of interferon (IFN) γ, tumour necrosis factor (TNF) α, interleukin (IL) 6, and IL-10 were significantly elevated due to infection with T. gondii alone, whilst the levels of IL-1α were down-regulated compared with other groups." (PMID 30186279, 2018). "Some Leishmania molecules, such as lipophosphoglycan (LPG), seem to repress IL1-α, IL-1-β and IL-12 production during infection via TLR2." (PMID 29379478, 2017). "Importantly, the wt and nga(G330D) strains induced comparable levels of IL-1α upon infection of macrophages, suggesting that increased IL-1β levels induced by the nga(G330D) strain is governed by a specific, likely posttranslational, mechanism." (PMID 28720729, 2017). "However, a significant increase in IL-1α and IL-10 levels was observed in LP infected animals due to the interaction between protein malnutrition and infection (p < 0.05)." (PMID 28397794, 2017). "Surprisingly, 6 months after infection, several proinflammatory genes were downregulated in peripheral blood cells of H. felis-infected Plcg2Ali5/+ mice as compared to infected WT mice, including two important inflammatory cytokines, IFNγ and IL-1a." (PMID 26966907, 2016). "Even though infecting mice with 107 CFU of KN99α caused the stimulation of both IL-1α and IL-1β, the levels were only comparable to those induced by infection with 106 CFU of the cda1Δ2Δ3Δ mutant, which was nonprotective." (PMID 27165801, 2016). "Interleukin 1 alpha (IL-1α) diverse pro-inflammatory cytokine that share several biological functions including in the encouragement of inflammatory response, maintain cellular immunity and provide host defense against infection." (PMID 27902750, 2016). "Interestingly, this increase in IL-1α is accompanied by a decrease in IL-6 expression, suggesting a shift in the nature of the response to these infections at later times." (PMID 26171605, 2015). "Specifically, TNF-α, GM-CSF, MIP-1α, IL-1α, IL-1β, IL-2, IL-3, IL-12p40, IL-12p70, and IL-17 levels were significantly reduced in UV-12 animals compared to vehicle control treated mice at both the 72 and 96 h post infection time points." (PMID 25984714, 2015). "In support of this, we observed that P. mirabilis causes more tissue damage and larger induction of the pro-inflammatory cytokines IL-1α, IL-β, IL-6, and G-CSF than does E. coli in independent infection, while a mixed infection appears more similar to E. coli alone." (PMID 25568946, 2015). "Nevertheless, IL-1α is stimulated during infections by SPN, GBS, and GAS." (PMID 26500655, 2015). "This coincides with a 6-fold increase in IL-1α as compared to the level at 12 h after infection." (PMID 26171605, 2015). "However, in our system IL-1α only stimulated more inflammation when there was endometrial cell damage as well as infection." (PMID 25395028, 2014). "Similarly, the proinflammatory cytokines IL-1α and IL-6 were mainly up-regulated by the swH1N1 infection." (PMID 24708855, 2014). "Interestingly, unlike what we see for dotA mutants, infection with Δ5 was still able to induce secretion of mature IL-1α at 24 hrs after infection, even though it was to a lesser extent than wild type." (PMID 25058342, 2014).
infection (continued). "Whilst the present study provides several lines of evidence for the role of IL-1α in endometrial cell responses to infection followed by cell damage, we cannot exclude the possibility that IL-1β may also be involved." (PMID 25395028, 2014). "Interestingly, IL-1α gene expression showed a dramatic increase in the cecal tissues of Sigirr −/− mice during infection." (PMID 23950714, 2013). "Both IL-1α and IL-1β are regarded as pro-inflammatory cytokines, but IL-1β rather than IL-1α has been more commonly associated with symptoms such as weight loss and fever that are induced by infection with a live virus or other immune stimulus." (PMID 23056330, 2012). "This was in contrast to IL-1α which was expressed only at low levels throughout the course of infection suggesting that IL-1β may play the predominant role in immunity against WNV." (PMID 23209411, 2012). "These processes are driven by IL-1α and IL-1β which signal through the IL-1R1 (IL-1Rα) and MyD88 to drive downstream NF-κB activation and subsequent expression of genes whose products regulate the immune response to infection." (PMID 23209411, 2012). "Moreover, the kinetics of IL-1α protein production is more rapid following infection with the galU mutant strain of FT." (PMID 21819572, 2011). "For 6 of the cytokines measured [IL-1a, IL-5, IL-10, IL-12(p40) and IL-12(p70)], the concentration in the supernatant dropped to a level which was below the detection limits for the particular assays by 15 min post H37Rv-infection." (PMID 22039457, 2011). "Likewise, human A/NY infection induced a significantly (p<0.05) higher level of basolateral IL-1α expression at 6 h and 24 h pi compared to mock controls." (PMID 21731666, 2011). "Similarly, the cytokines Il1α, Il5, Il6, and Il12 were secreted into the broncho-alveolar space of both strains after infection but were higher in DBA/2J mice." (PMID 19293935, 2009). "In the absence of infection, CF-TG cells constitutively exhibited an inflammatory signature, including genes that encode molecules such as IL-1α, IL-β, IL-32, TNFSF14, LIF, CXCL1 and PLAU." (PMID 19399182, 2009). "Il1a and Il1b transcription was measured four hours post-infection." (PMID 19043549, 2008). "However, the absence of IL-1β significantly impacted immune defense and led to elevated fungal growth in both the kidney and brain, which is consistent with a 107-fold higher induction of Il1b transcripts compared to Il1a transcripts during the first two days post-infection." (PMID 40097388, 2025). "However, since all three cytokines play an important role in host defense against infection as well as in the pathogenesis of autoimmune and inflammatory diseases, a therapy that concomitantly targets the release of IL-1α, IL-1β and IL-18 is of high clinical interest." (PMID 41221292, 2025). "Previous studies have shown that infection with highly virulent ASFVs including E70 (genotype I, Europe), Armenia 2008 (genotype II, Caucasus), and SY18 (genotype II, China) can cause increases in serum IL-1α and IL-1β, while moderately virulent and attenuated ASFV strains do not." (PMID 41156603, 2025). "Of note, the exaggerated neutrophil accumulation in Ccr2−/− mice has been reported in other inflammatory settings, including infection and injury models, suggesting that the IL-1α-mediated vicious cycle of inflammation identified in the present study may be operative in these settings as well." (PMID 38396021, 2024). "Notably, key inflammatory mediators, such as interleukin-1 (Il1a) and nitric oxide synthase 2 (Nos2) were up-regulated after infection in obese ferrets, possibly leading to extensive inflammatory damage of the respiratory epithelium as observed in histopathology." (PMID 38728395, 2024). "However, manipulation of these defenses and damage by the infection may lead to aberrant responses characterized by the unchecked release of pro-inflammatory cytokines such as IL-1α, IL-1β, TNFα, IFN-γ, and IL-6." (PMID 34440903, 2021).
infection (continued). "We therefore hypothesize that 2-methylpentane was associated with Up infection in a time-dependent manner and independent of the IL-1α mediated inflammatory pathway." (PMID 34368028, 2021). "However, in other studies, genetic deficiency or neutralization of IL-1α, but not of IL-1β, conferred higher susceptibility to infection." (PMID 34809460, 2021). "Additionally, tumor necrosis factor-alpha (TNF-α) and interleukin-1 alpha (IL-1α) production in tonsillar tissue cultures increased upon infection with human immunodeficiency virus-1 (HIV-1), which was found to have an impact on both innate and adaptive immune response." (PMID 33481814, 2021). "In addition, a disruption of the chemoattractant axis CCL20/CCR6 in Il1a-/- mice could explain the reduced Th17 response after 30 days of infection." (PMID 31425553, 2019). "However, the cerebral content of IL-1α and IL-1β, which contribute to a wide range of neurodegenerative conditions as well as acute and chronic neuroinflammatory processes, differed between both infection groups." (PMID 31315623, 2019). "Furthermore, most of the pro-inflammatory genes found on this array, which we have previously identified to be increased with 22L infection (such as Cxcl10, Ccl8, Tnf, IL1a, and IL1b), were similarly increased in the absence of TLR2 or C5aR1 signaling during scrapie infection." (PMID 30596651, 2018). "After the infection of untransfected and hBD-2- or hBD-3-transfected Caco-2 cells with E. faecium and/or S. typhimurium, we examined the host response by evaluating the expression of proinflammatory cytokines IL-6, IL-8 Il-1α, and IL-1β and anti-inflammatory cytokine TGF-β by real-time PCR." (PMID 29250559, 2017). "As IL-1α is one of the first cytokines to be released in response to infection, it could be that multiple pathways of activation ensure a maximal innate immune response in the early hours of infection, in case one route of IL-1α induction becomes blocked or is evaded by S. typhimurium." (PMID 28761045, 2017). "A recent study reported that Ft-specific IgM produced by B1a B cells was significantly reduced in Il-1b/-, Il-1b-/-/Il-1a-/-, or Il-1r1-/- mice compared to C57BL/6J wildtype or Il-1a-/- mice and implicated as an explanation for susceptibility of IL-1β-deficient mice to pulmonary Ft LVS infection." (PMID 27926940, 2016). "Besides chemokines, cytokines such as TNF-α are released acutely in response to injury or infection, and function to initiate and maintain the inflammatory process in part by stimulating other pro-inflammatory cytokines (e.g., IL-1α, IL-1β, and IL-6) and chemokines (e.g., CCL2, CCL3, and CXCL2)." (PMID 26860080, 2016). "Given the importance of IL-1α in a pulmonary granulomatous response, both the initial parenchymal cell type and the virulence of the mycobacteria infection may dictate the IL-1α levels within the CNS, and thus define both the form and course of the infection." (PMID 26041993, 2015). "Mice double deficient for IL-1α plus IL-1β could not control the infection, similar to IL-1R1 deficient mice on day 35 post-infection, although bacterial burdens were not as high as those reached in TNF KO mice which succumbed at 4 weeks." (PMID 25400917, 2013). "However, IL-1α release and cell death following infection with flagellin-deficient L. pneumophila are independent of NLRP3, indicating that caspase-11 also mediates an NLRP3-independent response towards flagellin-deficient L. pneumophila." (PMID 23762026, 2013). "However, mice singly deficient for either IL-1α or IL-1β survived for the duration of the acute M. tuberculosis infection study (3 months) without clinical symptoms of infection." (PMID 25400917, 2013). "Infection of NHBE cells by HRV is thus likely associated with recognition of viral products, oligomerisation of the inflammasome resulting in caspase-1 activation and release of mature IL-1β and IL-18, but also an alternative active process resulting in IL-1α release." (PMID 23723976, 2013).
infection (continued). "Here we have shown that after infection of non-vaccinated Tlr4-deficient mice the number of bacteria, and lung IL-1α and IL-1β expression are higher than in similarly treated wild-type controls, while bronchial LN cell IFN-γ and IL-17 production and splenocyte TNF-α production are lower." (PMID 18498620, 2008). "We supplemented mice with topical vaginal recombinant IL-1α beginning one day prior to GBS infection and daily throughout the infection time course." (PMID 41542635, 2026). "No significant cytokine differences were observed at 7 dpi even though GBS burdens were higher in HFHS-fed mice at that timepoint, but we did note differential IL-1α fluctuation between HFHS and control mice over the course of infection." (PMID 41542635, 2026). "As expected, C. albicans induced higher levels of G-CSF, IL-6, IL-1α, and IL-1β than N. glabratus cells in an in vitro OEC infection model." (PMID 40233931, 2025). "Gene expression of interleukin (IL)-6, IL-8, TLR2, TLR4, IL-1 alpha (IL-1α), and CXCR1 was evaluated by quantitative real-time polymerase chain reaction at 0, 6, 12, 24, 48, and 72 h post-infection." (PMID 40453956, 2025). "A suppressed number of antiviral cytokines like IL-1a, IFN-β, and especially TNF-α is observed in transduced cells after 24 h of infection." (PMID 41157608, 2025). "Infection with GB112 resulted in elevated production of EGF, IL-1α, IL-10, sCD40L, and fractalkine in the maternal and fetal chambers of the organ-on-a-chip models, but not in the primary human gestational membranes." (PMID 41277827, 2025). "To determine the influence of coexistent Ss infection on type 1, type 17, and proinflammatory cytokines in TBI, we measured the QFT supernatants levels of IFN-γ, TNF-α, IL-2, IL-17, IL-22, IL-1α and IL-1β in TBI+Hel+ and TBI+Hel- individuals." (PMID 41583474, 2025). "Analysis of inflammatory mediators in NHBE culture supernatants (Luminex multiplex assay) revealed that IL1β, IL1α, and CXCL1 were significantly elevated in NHBEA/A cultures compared to NHBEG/G cultures following infection with Cal/09 and HK/68." (PMID 40627391, 2025). "Infection of PNEs with RV-A16 at MOI 0.01 or MOI 1 for 24 h resulted in the upregulation (> twofold) of 6 cytokines (IL-1β, IL-1α, IFN-γ, I-309, TNF-α and IL-11)." (PMID 40916026, 2025). "Upon infection of PBMCs, HIV-1ADA induced significantly higher levels of pro-inflammatory cytokines IL-1α, IL-1β, IL-6 and TNF-α as measured via Luminex assay." (PMID 40313367, 2025). "Infection with SARS-CoV-2 showed a decreased expression of IL-6 measured at 3 and 24 hpi and of IFNα at 3 hpi and IL-1α at 24 hpi compared to uninfected control cells." (PMID 39772252, 2024). "Corresponding with the increased gene expression of Il1a and Tnfa, IL-1α and TNF- protein in the airways was also significantly elevated on day 1 post infection in mice exposed to LPS before RSV infection compared to LPS only and RSV only mice." (PMID 39127259, 2024). "During in vivo infection, pigs infected with highly virulent strains of ASFV exhibit elevated systemic production of IFN, TNF-α, IL-1α, IL-1β, and IL-6, mainly facilitated by NF-κB or alternative transcription factors." (PMID 38846950, 2024). "In contrast, IL-1α was decreased at day 4 after infection, whereas IL-5, CCL3, CCL4 (MIP-1β), and IFN-γ were significantly reduced in IkkαLyve-1 BALF at day 7 after infection." (PMID 39007717, 2024). "Inflammatory MoDCs are multifunctional and express IL-1α, IL-1β, IL-10, TNF-α, and inducible nitric oxide synthase (iNOS) in the lungs between 2 and 3 weeks after infection with M. tuberculosis." (PMID 37686061, 2023). "The HLA-A11/DR1 mice strain induced lower levels of several cytokines (IL-2, IL-10, IL-18, IL-1β, TNF-α, IL-1α, IL-28, and ENA78), but showed increased secretion of IFN-γ, RANTES, IP10, and Eotaxin at 12 h post-infection, compared to the WT group." (PMID 38035330, 2023).
infection (continued). "While the levels of both mRNA and secreted protein for IL-1α and CXCL8 increased in response to infection, the levels of CXCL10 and CCL20 in the culture supernatant decreased." (PMID 37067432, 2023). "Infection with ply+lytA+ strain A66 induced detectable IFNγ, IL-6, TNFα, RANTES, IL-1α and IL-1β in the lungs of inoculated mice, and all but IL-1α in the bloodstream." (PMID 36897919, 2023). "To assess the immunological response of C57BL/6J- Cftrtm1UncTg(FABPhCFTR)1Jaw/J mice to S. maltophilia and P. aeruginosa polymicrobial infection, we measured inflammatory markers in the BALF by multiplex assay for IL-1α, IL-1β, IL-6 and TNF-α." (PMID 36748431, 2023). "Infection with virulent ASFV isolates often results in exacerbated immune responses, with increased levels of serum pro-inflammatory interleukins (IL-1α, IL-1β, IL-6), TNF and chemokines (CCL2, CCL5, CXCL10)." (PMID 36680273, 2023). "We analyzed hLO culture supernatants for the presence of ten cytokines and chemokines commonly produced by epithelial cells in response to infection (TNF-α, IFN-α2a, IFN-β, IFN-λ1, IL-8, IL-1α, IL-1β, IL-6, IP-10, MCP-1)." (PMID 37883246, 2023). "During inflammation, there is the recruitment of immune cells at the infection site, which are the target of the infection, and the production of cytokines, such as TNF and IL-1a, responsible for the disruption of epithelial barrier integrity." (PMID 36798134, 2023). "Infection with KSHV induces high levels of pro-inflammatory cytokines, chemokines and angiogenic factors such as TNF, IL-1α, IL-1β, IL-6, CXCL8, IFN-γ, VEGF, COX-2 and GM-CSF." (PMID 36634147, 2023). "This study analyzes the efficacy of LL-37 cream in enhancing wound healing rate and decreasing the levels of IL-1α, TNF-α, and the number of aerobic bacteria colonization in DFU with mild infection." (PMID 37480520, 2023). "Our study revealed top 8 cytokines (IL-17, IL-1α, IL-2, IL-10, IL-5, IFN-γ, TNF-α and IL-6) and their biomarker abilities to discriminate different stages of infection." (PMID 36646786, 2023). "We found that the levels of proinflammatory chemoattractant cytokines like IL-1α, MCP-1, and KC, as well as cytokines produced by macrophages and PMN in response to infection (IL-1 and IL-6), were increased in TBI/PAO1-infected mice." (PMID 35041620, 2022). "Remarkably, the knockdown of Nbeal2 significantly promoted the production of IL-1α, IP-10, IL-6, CCL-4 and TNF-α at 24 h post-infection in P815 cells infected with H1N1 virus and H5N1 virus." (PMID 35215885, 2022). "Under the stimulus of the G/478 K.V1/ B.1.617.2 strain infection, the mRNA expression of IL-6, IP-10, CCL-5 and IL-1α significantly was increased after infection for 48 h compared with NC group (P < 0.001)." (PMID 35365215, 2022). "After infection, several additional pro-inflammatory upstream regulators including PTGS2 (COX2), IL1A, TNF, and SPI1 (PU.1) were activated at higher levels in aged mice." (PMID 35614490, 2022). "Both IL-1α and IL-1β induce local inflammation and the recruitment and activation of neutrophils, monocytes and macrophages, which might act as a double-edged sword, limiting on infection the one hand and activating inflammation-related local and systemic damage on the other." (PMID 36551320, 2022). "As observed by us too with Mtb-HT and Mtb-LT infections, the similar IFN expression between WT and Il1a−/−Il1b−/− mice was seen at 30 days post-infection, most likely a reflection of the increased bacterial burden." (PMID 35173157, 2022). "The other notable findings in our agarose bead inoculum experiment were the significantly elevated levels of IL-1α and TNFα in IFT88 KO mice relative to control mice at day 15, with the difference still present and significant at day 54 after infection." (PMID 36505420, 2022). "The increase in IL-1α, IL-6, KC, MCP-1, G-CSF, and eotaxin was abolished in Trpm5–/– mice after infection." (PMID 35503420, 2022).